NRAS (NRAS proto-oncogene, GTPase)
Diseases named in the same sentence as NRAS in open-access papers (continued):
Sharing a sentence is not in itself a finding about the gene and the disease.
melanoma (continued). "We identified five cases with NRAS mutations (5/11;45%) and two cases with KRAS mutations (2/11;18%) in the melanomas of nasal cavity." (PMID 34102999, 2021). "A Phase 1b/2 trial evaluating the combination of ribociclib with binimetinib in NRAS-mutant melanoma recently reported their results from 41 patients treated on a 28-day schedule Phase 2 dose expansion cohort." (PMID 33456709, 2021). "NRAS mutation significantly correlated with worse OS (p = 0.026) and worse MSS (p = 0.031) for all cases of mucosal melanomas." (PMID 34571863, 2021). "NRAS mutant melanoma cell growth and survival relies on continual NRAS expression, implying that USP9X-mediated stabilisation of ETS-1 drives tumorigenesis." (PMID 34066106, 2021). "We collected information on the mutation status of BRAF, NRAS and NF1 genes for SKCM TCGA samples and investigated the association between isomiR expression and the most clinically relevant mutations in melanoma." (PMID 34698264, 2021). "Nearly 45% of melanoma lines showed BRAF-activating mutations, and 20% showed NRAS-activating mutations; both mutations activate the ERK/MAPK (mitogen-activated protein kinase) pathway." (PMID 34577571, 2021). "As expected, KRAS mutation dependence was observed in colon, pancreatic and lung cancer cell lines, NRAS mutation dependence in melanoma lines, and BRAF mutation dependence in colon, thyroid and melanoma lines." (PMID 34254730, 2021). "The RAC1 P29S mutation is more frequent in melanomas BRAF and NRAS wild-type and occurs early in tumorigenesis." (PMID 34123788, 2021). "A combination of ribociclib (a CDK4/6 inhibitor) and a MEK inhibitor (binimetinib) was evaluated in a phase 1b/2b trial in 63 patients with NRAS mutant melanomas, obtaining an ORR of 19.5% (n = 41) and a PFS of 3.7 months in the phase 2 expansion." (PMID 34831002, 2021). "For instance, interferon alpha-inducible protein 6 (IFI6) is reportedly necessary for oncogenic NRAS-induced transformation and melanoma growth." (PMID 34650128, 2021). "Pan-RAF inhibitors, such as belvarafenib, which can target BRAFV600E, the BRAF wild-type, and CRAF have shown anti-tumor efficacy in NRAS mutant melanomas in a phase 1 dose escalation study with an ORR of 44%." (PMID 34831002, 2021). "Consistently, NRAS protein levels were increased in melanoma cells overexpressing RP11-705C15.3 and decreased in melanoma cells silencing RP11-705C15.3." (PMID 33311650, 2021). "Here, we show that combining TRT with MEKi can overcome such activation by reducing ERK phosphorylation in BRAF- and NRAS-mutant melanoma." (PMID 33804655, 2021). "While drugs targeting the MAPK pathway have yielded success in BRAFV600 mutant melanoma patients, such therapies have been ineffective in patients with NRAS mutant melanomas in part due to their cytostatic effects and primary resistance." (PMID 33921974, 2021). "Belvarafenib is a selective RAF dimer (type II) inhibitor with clinical efficacy in BRAF and NRAS-mutant melanomas." (PMID 34804979, 2021). "These proteins have been found to be overexpressed in NRAS mutant melanoma; moreover, a combination of BET and MEK inhibition showed antitumor effects in otherwise MEKi-resistant tumors." (PMID 34830283, 2021). "LXH254 is being further investigated in combination with a MEK inhibitor (trametinib), an Erk inhibitor (LTT462) or a CDK inhibitor (ribociclib) in patients with NRAS mutant melanoma (NCT02974725, NCT04417621)." (PMID 34946644, 2021). "CCG-222740, a compound that inhibits Rho/MRTF-mediated gene transcription, markedly increased the efficacy of trametinib on NRAS-mutant melanoma cell lines." (PMID 33921974, 2021).
melanoma (continued). "The tumorigenesis of melanoma is associated with several gene mutations in BRAF, NRAS and C-KIT, which are correlated with the histopathological characteristics of melanoma." (PMID 34069297, 2021). "Based on these findings, it is very unlikely that inclusion of NRAS mutant melanomas negatively impacted our results." (PMID 33915880, 2021). "In advanced Asian melanoma treated with anti-PD-1 monotherapy, NRAS mutant patients had lower response rates and poorer prognoses compared to wild-type patients, especially in noncutaneous subtypes." (PMID 34290710, 2021). "Alterations in CDKN2A and in CCND1 are present in NRAS mutant melanomas in 70% and 10% of cases, respectively." (PMID 34831002, 2021). "The combat of melanoma by using the targeted therapy is impeded because several major driver mutations fuel its growth (predominantly BRAF and NRAS)." (PMID 34063141, 2021). "We observed a remarkable upregulation of several isomiRs from the miR-17-92 cluster in NRAS mutant melanomas." (PMID 34698264, 2021). "While most of this work focused on BRAF melanoma cell lines, MEK inhibition in NRAS mutant melanoma cell lines was also found to activate cytoprotective autophagy through ERK reactivation." (PMID 34830283, 2021). "Several large-scale sequencing studies in melanoma identified significantly mutated melanoma genes, such as NF), ARID2, TERT or RAC beside the well-established oncogenes including NRAS, BRAF or KIT." (PMID 33578810, 2021). "By considering both PLA1A mRNA and serum levels simultaneously, PLA1A levels were significantly increased in BRAF/NRAS+ melanoma patients (p ≤ 0.05)." (PMID 33723350, 2021). "We identify ID3 as a novel client protein of HSP70, and show that the HSP70 inhibitor AP-4–139B synergizes with MEK inhibitors against NRAS-mutant melanoma in vivo." (PMID 35187538, 2021). "Taken together, these results indicate that the Rho/MRTF pathway is activated in NRAS mutant melanoma cell lines having intrinsic resistance to trametinib-induced inhibition of cell proliferation." (PMID 33921974, 2021). "What should also be noticed is belvarafenib, a potent and selective RAF dimer (type II) inhibitor, exhibits clinical efficacy in patients with BRAFV600E and NRAS-mutant melanomas." (PMID 34924562, 2021). "As no therapeutic agents have been approved specifically for NRAS-mutant melanoma, our aim was to compare the benefit of PLA1A in the BRAF- and NRAS-driven melanoma cancer population." (PMID 33723350, 2021). "We examined Usp9x and SOX2 expression levels in a panel of BRAF- and NRAS-mutant melanoma cell lines." (PMID 33613844, 2021). "In melanoma, the Phosphoinositide 3-kinase (PI3K)/AKT pathway is implicated in mutations in phosphatase and tensin homologue (PTEN) and NRAS, which occur most frequently after BRAF mutations." (PMID 33833342, 2021). "A retrospective study of 217 patients confirmed that, compared to BRAF-mutant and -wild-type melanomas, NRAS-mutant tumors show a more aggressive biological behavior." (PMID 34209415, 2021). "TERT promoter mutations result in several cancer types, including melanoma, and the simultaneous presence with BRAF/NRAS alterations is associated with poor prognosis for the patients." (PMID 33917181, 2021). "The aim of our study was to evaluate the prognostic value of BRAF and NRAS mutation, evaluated in everyday clinical practice, in relation to the most important prognostic parameters, especially, the SLN status of melanoma patients." (PMID 34209415, 2021). "Subsequent TBK1 downregulation inhibits cell migration and invasion, whereas its overexpression increases invasion of NRAS mutant melanoma cells." (PMID 34063141, 2021).
melanoma (continued). "For example, this combination has shown synergy in preclinical KRAS mutant colorectal cancer models, and is efficacious against a subset of NRAS and other melanoma subtypes." (PMID 34025662, 2021). "Collectively, these findings suggested that RP11-705C15.3 activated NRAS/MAPK signaling in a miR-145-5p dependent manner in melanoma." (PMID 33311650, 2021). "We established eleven new melanoma primary cultures from metastatic lesions harboring different oncogenic BRAF and NRAS driver mutations, all explanted in both Ham’s F10 culture medium with 10 or 100 μM tyrosine." (PMID 34869032, 2021). "Vemurafenib and MEKi treatment induced SOX2 in a time-dependent manner in both BRAF- and NRAS-mutant melanoma." (PMID 33613844, 2021). "The involvement of HULC in the tumorigenesis of a subset of NRAS‐mutant melanomas appears to be unreported and merits further investigation as a possible novel discovery with therapeutic implications." (PMID 33769711, 2021). "BRAF, MEK, NRAS, HRAS, KRAS, c-KIT, c-Met, VEGFR, PTEN, and PIK3CA mutations are common in melanoma." (PMID 34804979, 2021). "NRAS and NF1 mutations are less frequent than BRAF mutations, occurring in approximately 10-25% and 14% of melanomas, respectively." (PMID 34025662, 2021). "NRAS-mutant melanomas preferentially localize to chronically sun-damaged (CSD) skin on the head and neck, whereas BRAF-mutant melanomas are more common in areas of intermittent sun exposure." (PMID 34210801, 2021). "Another prospective cohort study suggested that melanoma patients with BRAF and NRAS mutation had an increased risk of tumor recurrence following a negative sentinel lymph node status." (PMID 34209415, 2021). "In a retrospective study, 11 patients with NRAS mutant melanoma and 37 wild-type patients received anti-PD-1 monotherapy." (PMID 34290710, 2021). "Oncogenic mutations in RAS genes (KRAS, NRAS, and HRAS) or RAF genes (RAF-1, BRAF, and A-RAF) occur in many cancer types, including the melanoma cells." (PMID 34822435, 2021). "These NF1 mutations are more common in melanomas occurring on chronically sun-exposed skin or in older patients, in melanomas with higher mutation burden, wild-type for BRAF and NRAS, and in the desmoplastic melanoma subtype." (PMID 34123788, 2021). "MAPK activation has been recognized as a key regulator of tumor biology in malignant melanoma and is the most common dysfunctional pathway within melanoma tumorgenesis, typically via the BRAF or NRAS mutations." (PMID 34155457, 2021). "In this work, we showed using 3D in vitro tumor models, an additive efficiency of combining [131I]ICF01012-TRT and MAPK/ERK inhibitors in BRAF- and NRAS-mutant melanoma cells." (PMID 33804655, 2021). "Using The Cancer Genome Atlas (TCGA) dataset of skin cancers, we analyzed isomiR expression in primary melanoma and melanoma metastasis and tested their association with NF1, BRAF and NRAS mutations." (PMID 34698264, 2021). "The CDKN2A/CDK4/6 pathway has a role in the G1–S transition in the cell cycle, which is dysregulated in BRAF and NRAS mutant melanomas." (PMID 34831002, 2021). "Celecoxib (50 nM) and trametinib (25 nM) therapeutic association was tested in vitro on a simulated melanoma tumor formed of SK-MEL-28 human melanoma cells (positive for BRAF V600E and wild type NRAS mutations) and BJ human fibroblasts, used as co-culture." (PMID 33922284, 2021). "In melanoma, although present in much lower percentages compared to BRAF and NRAS mutations, in the last few years, several mitogen-activated protein kinase kinase (MEK) mutations have been identified." (PMID 33917181, 2021). "Female patients more frequently harbored BRAF V600E mutant melanoma (46% versus 36%), while BRAF V600K and NRAS mutations were more prevalent in the tumors of male patients (8% versus 4% and 21% versus 18%, respectively)." (PMID 34572865, 2021). "Mutations in key genes of the MAPK/ERK pathway, namely NF1, NRAS and BRAF, identify three main molecular subtypes of melanoma." (PMID 34698264, 2021).
melanoma (continued). "One clinical study compared prognostic significance between a cohort of BRAF-mutant and NRAS-mutant melanoma patients, revealing a lower relative survival in patients with NRAS-mutant melanoma." (PMID 33807778, 2021). "The observed radio-sensitization in BRAF- and NRAS-mutant melanoma cells lines treated with TRT and MEKi combination will need, in the future, to be assessed by in vivo studies using human BRAF- and NRAS-mutant melanoma xenografts." (PMID 33804655, 2021). "The MAPK pathway is almost universally hyperactivated in melanoma, owing to the frequent activating mutations in BRAF and NRAS." (PMID 33808771, 2021). "In NRAS mutant melanomas, the inhibition of PKA signaling (that prevents CRAF inactivation) leads to the negative feedback inhibition of BRAF and promotes CRAF-mediated MAPK signaling instead." (PMID 34831002, 2021). "Next, we analyzed C > T transitions in four mutational subtypes of melanoma, BRAF-, NRAS-, NF1-mutant samples and triple-wildtype samples." (PMID 33578810, 2021). "Another ERKi, ulixternib, is an ATP-competitive ERK1/2 inhibitor, and its phase I/II clinical trial showed an 18% response rate in NRAS mutant melanoma patients." (PMID 34830283, 2021). "The frequency of NF1 mutations in melanomas is approximately 15%, with a higher frequency observed in older patients, chronic sun damage lesions, desmoplastic melanomas, and BRAF/NRAS wild-type melanomas (a frequency of 70%)." (PMID 34831002, 2021). "We have previously demonstrated that SIRT3 knockdown in NRAS-mutant SK-MEL-2 human melanoma cells inhibited tumor growth in a subcutaneous implanted Nu/Nu nude mouse model." (PMID 33937086, 2021). "Some retrospective studies have investigated the response and outcome of immunotherapy for NRAS mutant melanoma." (PMID 34290710, 2021). "One melanoma carried a BRAF V600E mutation (p.Q61R), and two melanomas carried a NRAS mutation (p.G12D)." (PMID 34065883, 2021). "A phase 1 study with an antibody targeting ERBB3 in combination with trametinib in NRAS mutant or wild-type melanomas was terminated in 2020 (NCT03580382)." (PMID 34831002, 2021). "Further, for NRAS-mutant melanoma, binimetinib reportedly improves progression-free survival compared with dacarbazine." (PMID 34525976, 2021). "Our group has analyzed the transcriptomes of 92 single cells cultured from a patient biopsy of a BRAF wild type/NRAS wild type melanoma metastasis by scRNA-seq." (PMID 33535416, 2021). "In contrast, there was no significant decrease in cell viability in the NRASQ61L mutant (WM1366) or BRAF/NRAS wild-type (WM3211) melanoma cell line." (PMID 34885166, 2021). "Interaction of total RPS3 with HNRNPU showed a decrease in the cytoplasmic fraction of NRAS mutant melanoma cells treated with MEKi and in BRAF mutant cells treated with combination mBRAFi/MEKi as assessed by PLA analysis." (PMID 34070332, 2021). "In total, 28% (3/18) of acral melanomas showed either a KRAS or NRAS mutation (11% KRAS mutation, 17% NRAS mutation)." (PMID 34102999, 2021). "Anti-tumour effects of miRNA-145-5p in human melanoma cell lines and xenograft tumours involve targeting NRAS transcripts to suppress cell proliferation mediated by the MAPK pathway." (PMID 34822659, 2021). "In this study, we show that NRAS mutant human melanoma cells that are most resistant to inhibition of the oncogenic pathway have a second activated pathway (Rho)." (PMID 33921974, 2021). "To uncover potential tumor-intrinsic mechanisms that regulate TLS formation, we have taken the novel perspective of evaluating TLS induction in melanomas impacted by common driver mutations in BRAF, PTEN, NRAS, KIT, PRDM1, and MITF." (PMID 33746966, 2021). "KRAS is common in pancreatic adenocarcinomas and colorectal cancer, NRAS in melanoma, thyroid cancer, and leukemia." (PMID 34604242, 2021).
melanoma (continued). "This research shows a synergistic effect of combining HSP70 inhibitors with MEKi for the treatment of NRAS mutant melanoma." (PMID 35187538, 2021). "A previous phase II study of binimetinib revealed that 20% of advanced NRAS-mutant melanoma patients generated a partial response to treatment, and 43.3% displayed stable disease." (PMID 33807778, 2021). "Other studies using NGS and cancer hotspot panels in paired melanoma samples found the same main driver mutations (BRAF, NRAS, KIT)." (PMID 34680222, 2021). "In summary, we identified RP11-705C15.3 as a prognosis-related and oncogenic lncRNA in melanoma through competitively binding miR-145-5p and activating NRAS/MAPK signaling axis." (PMID 33311650, 2021). "We compared the results in the UM cell lines with the effect on cell lines with a BRAF or NRAS mutation (i.e. melanoma cell line OCM3 [BRAF-mut] and the CoM cell lines CRMM1 [BRAF-mut] and CRMM2 [NRAS-mut])." (PMID 33798262, 2021). "The most common genetic subtypes of human melanoma, neuroblastoma RAS viral oncogene homolog (NRAS)- and v-Raf murine sarcoma viral oncogene homolog B (BRAF)-mutant, are enriched in different anatomical locations." (PMID 34210801, 2021). "Among RAS isoforms, KRAS mutations are most frequently found in pancreatic, colorectal and lung adenocarcinomas, while NRAS and HRAS are generally mutated in some melanomas, leukemias and thyroid cancers." (PMID 34946644, 2021). "The study partitioned melanoma tumors (both primary and metastatic) based on the pattern of the most prevalent mutated genes into four subtypes: BRAF, NRAS, NF1, and WT." (PMID 33564068, 2021). "These alterations seem to vary in frequency depending on the melanoma subtype and are mutually exclusive to BRAF and NRAS mutations, with rare exceptions." (PMID 34831002, 2021). "In turn, BRAF mutations are the dominating genetic causative factor in superficial spreading melanoma (SSM), whereas for ALM, typical mutations can be found in the BRAF, NRAS, KIT, and NF1 genes." (PMID 34575876, 2021). "A combination of trametinib with the Rho/MRTF-pathway inhibitor, CCG-222740, synergistically reduced cell viability in NRAS mutant melanoma cell lines in vitro." (PMID 33921974, 2021). "In the present NRAS-mutant melanoma model, [131I]ICF01012-TRT dramatically increased mouse survival and reduced tumor growth." (PMID 33804655, 2021). "For melanoma, mutations in the key signal components, including BRAF, NRAS, NF1, and KIT, are responsible for the hyper-activation of the MAPK pathway." (PMID 34924562, 2021). "The combination of CCG-222740 with low concentrations of trametinib is able to suppress clonogenicity and induce the apoptosis of a highly aggressive NRAS mutant melanoma." (PMID 33921974, 2021). "Our data show that advanced melanoma in women more frequently harbors a BRAF V600E mutation, while melanoma in men more frequently has a NRAS or BRAF V600K mutation." (PMID 34572865, 2021). "The MAPK and PI3K pathways overlap in melanoma and therefore some signaling mediators such as NRAS act through both pathways." (PMID 35127523, 2021). "The current standard-of-care for BRAF mutant melanoma is a combination of BRAF and MEK inhibitors, and this combination with the addition of a CDK4/6 inhibitor induces sustained tumour regression in both BRAF and NRAS mutant melanoma preclinical models." (PMID 33572972, 2021). "On the other hand, considerable exploration of combination therapy in NRAS mutant melanoma has been conducted." (PMID 34290710, 2021). "Melanomas are most frequently characterized by BRAF and NRAS mutation and, more rarely, by c-KIT oncogene mutations, but tumor suppressor genes such as CDKN2A and PTEN have an important role in the development and prognosis of melanoma." (PMID 34209415, 2021). "The aim of our study was to assess the correlation between known prognostic factors of melanoma, mutational occurrence of BRAF and NRAS in the primary tumor, and sentinel lymph node status." (PMID 34209415, 2021).